CTU2 (cytosolic thiouridylase subunit 2)
Description:
Plays a central role in 2-thiolation of mcm(5)S(2)U at tRNA wobble positions of tRNA(Lys), tRNA(Glu) and tRNA(Gln). May act by forming a heterodimer with CTU1/ATPBD3 that ligates sulfur from thiocarboxylated URM1 onto the uridine of tRNAs at wobble position.
Synonyms: C16orf84; NCS2; MFRG; UPF0432
Tractability: PROTAC: ubiquitination databases record sites on it; its protein half-life has been measured.
Gene: Protein-coding gene on chromosome 16 (88,706,473 to 88,715,396, forward strand). Ensembl gene ENSG00000174177.
Subcellular location: Cytoplasm
Subcellular location (Human Protein Atlas): Cytosol; Mitochondria
Pathways (Reactome):
Metabolism of RNA: tRNA modification in the nucleus and cytosol
Gene Ontology:
Molecular function: protein binding; nucleotidyltransferase activity; tRNA binding
Biological process: tRNA thio-modification; tRNA wobble position uridine thiolation; tRNA wobble uridine modification; protein urmylation
Cellular component: cytosol; protein-containing complex; cytoplasm
Genetic constraint (gnomAD): Loss-of-function variants: 81 observed, 63.48 expected, observed/expected ratio (o/e) 1.28, 90% interval 1.07 to 1.53. The synonymous counts are far from expectation, so gnomAD's model fits this gene poorly and the ratio says little. Missense variants: 1,110 observed, 681.23 expected, observed/expected ratio (o/e) 1.63, 90% interval 1.55 to 1.71. Synonymous variants: 482 observed, 284.16 expected, observed/expected ratio (o/e) 1.7, 90% interval 1.57 to 1.83.
Homologues: Orthologues: chimpanzee CTU2 (99% identical), guinea pig CTU2 (77% identical), mouse Ctu2 (77% identical), rat Ctu2 (77% identical), macaque CTU2 (74% identical), pig CTU2 (73% identical), dog CTU2 (71% identical), tropical clawed frog ctu2 (48% identical), zebrafish ctu2 (47% identical), Drosophila melanogaster Ctu2 (23% identical), Caenorhabditis elegans tut-2 (18% identical).
Diseases named in the same sentence as CTU2 in open-access papers:
CTU2 is named in the same sentence as 42 diseases in open-access papers, as found by Europe PMC text mining. Sharing a sentence is not in itself a finding about the gene and the disease. The quoted sentences say what the papers report.
melanoma (6 papers, 2018 to 2025). A malignant, usually aggressive tumor composed of atypical, neoplastic melanocytes. "Cytosolic thiouridylase 2 (CTU2) is an enzyme modifying transfer RNAs post-transcriptionally, which has been implicated in breast cancer and melanoma development." (PMID 38630355, 2024). "The enzymatic subunits of the elongator complex ELP1 and ELP3 and the thiolase CTU2 are overexpressed in human melanoma, particularly in melanomas carrying the BRAFV600E mutation." (PMID 33564819, 2021). "Besides, one study reveals that CTU2-linked tRNA modification promotes melanoma growth by regulating HIF1α codon-dependent translation." (PMID 38630355, 2024). "We found that melanoma and kidney cancer patients with high CTU2 expression had poorer survival prognosis and lower response rates to anti-PD-1 immunotherapy." (PMID 40375999, 2025). "We first investigated the predictive value of CTU2 in real-world immunotherapy response by incorporating data from two independent immunotherapy studies (GSE91061-melanoma; RCC-Braun_2020)." (PMID 40375999, 2025). "A high level of CTU2 expression is observed in breast cancer and melanoma tissue and CTU2 promotes the development of subcutaneous breast tumor and melanoma tumor transplantation." (PMID 38630355, 2024). "However, patients with low CTU2 levels demonstrated a higher likelihood of responding to immunotherapy, as evidenced by improved prognosis in melanoma and renal cell carcinoma when treated with anti-PD-1 therapy, compared to those with high CTU2 levels." (PMID 40375999, 2025). "Furthermore, studies have found that CTU2 is highly expressed in BRAFV600E-expressing melanoma cells, potentially promoting glycolysis by codon-biased regulation of HIF1α mRNA translation, which is rich in U34 codons, and maintaining high levels of HIF1α protein." (PMID 40375999, 2025). "Additionally, silencing of either ELP3 or CTU2 (s 2U) in human melanoma cells resulted in the induction of endogenous protein aggregates, suggesting the effect of Elongator and tRNA thiolation defects on protein solubility to be general and highly likely disease relevant." (PMID 30597914, 2018). "Multiple GEO datasets from the TIDE website further validated poor prognosis in patients with high CTU2 mRNA levels in BRCA, COAD, DLBC, LUAD, SARC, and melanoma." (PMID 40375999, 2025). "The most significant differences in melanoma are NOMO1, PIGT, VKORC1, PDIA5 and DDX11, and the most significant differences in uterine cancer are CTU2, EMC8, TUBG1, CLPP and LONP1." (PMID 34951103, 2022). "ELP1, ELP3, CTU1 and CTU2 are strongly upregulated in BRAFV600E cells and inactivation of ELP3 impaired the development of BRAFV600E melanoma in a zebrafish model." (PMID 30597914, 2018).
hepatocellular carcinoma (3 papers, 2024 to 2025). A malignant tumor that arises from hepatocytes. "Furthermore, the nearby CTU2 gene has been implicated in hepatocellular carcinoma development." (PMID 40564925, 2025). "Recent research has elucidated the role of CTU2 in hepatocellular carcinoma development and its upstream transcriptional regulatory mechanisms, identifying it as a Liver X receptor (LXR) target gene." (PMID 40375999, 2025). "And we found CTU2 participated in hepatocellular carcinoma (HCC) progression here." (PMID 38630355, 2024).
breast carcinoma (2 papers, 2024 to 2025). "Analysis of seven GEO datasets confirmed elevated CTU2 expression in breast cancer (BRCA), colon adenocarcinoma (COAD), LIHC, non-small cell lung cancer (NSCLC), esophageal cancer (ESCA), KIRC, and adrenocortical carcinoma (ACC)." (PMID 40375999, 2025).
microcephaly (2 papers, 2020 to 2024). A congenital or acquired developmental disorder in which the circumference of the head is smaller than normal for the person's age and sex. "Biallelic variants in CTU2 have been associated with a specific syndromic phenotype featuring microcephaly, facial dysmorphism, renal agenesis, and ambiguous genitalia, and this gene has been recently listed into the Developmental Disorders Genotype-Phenotype Database (DDG2P)." (PMID 32604767, 2020). "Meanwhile, homozygous Ctu2 mutation was identified in patients diagnosed with a novel multiple congenital anomalies syndrome called DREAM-PL which is characterized by dysmorphic facies, renal agenesis, ambiguous genitalia, microcephaly, and lissencephaly." (PMID 39705244, 2024).
breast tumor (1 paper, 2024). "In addition, CTU2 is elevated in breast tumors and promotes metastasis through supporting specific translation of oncogenic factor LEF1 in an internal ribosome entry site (IRES) dependent manner." (PMID 38630355, 2024).
cholangiocarcinoma (1 paper, 2025). A carcinoma that arises from the intrahepatic biliary tree (intrahepatic cholangiocarcinoma) or from the junction, or adjacent to the junction, of the right and left hepatic ducts (hilar cholangiocarcinoma). "This investigation revealed significant differential expression of CTU2 across 24 cancer types, with fold changes exceeding 2 in diffuse large B-cell lymphoma (DLBC), thymoma (THYM), cholangiocarcinoma (CHOL), and glioblastoma multiforme (GBM)." (PMID 40375999, 2025).
Cohen syndrome (1 paper, 2022). Cohen syndrome (CS) is a rare genetic developmental disorder characterized by microcephaly, characteristic facial features, hypotonia, non-progressive intellectual deficit, myopia and retinal dystrophy, neutropenia and truncal obesity. "The following genes were identified in 6 patients: cytogenetic band 6q21, PTRHD1, 22q11.23 deletion, Cohen syndrome, CTU2 gene, GABRA1 gene, and tuberous sclerosis." (PMID 35756865, 2022).
liver cancer (1 paper, 2025). An epithelial or non-epithelial malignant neoplasm that arises from the liver. "To validate this, we conducted in vivo experiments and found that knocking down CTU2 expression in Hepa1-6 (mouse liver cancer cell line) significantly reduced the number of tumor lesions in liver cancer orthotopic models." (PMID 40375999, 2025).
lung adenocarcinoma (1 paper, 2025). A carcinoma that arises from the lung and is characterized by the presence of malignant glandular epithelial cells. "Consistently, immunohistochemical data from the HPA databases confirmed increased CTU2 protein levels in BRCA, COAD, LIHC, and lung adenocarcinoma (LUAD)." (PMID 40375999, 2025).
lung carcinoma (1 paper, 2021). "It is worthwhile to determine crosstalk and functional roles between METTL1, CTU2, and XPOT in human cancer, notably lung cancer." (PMID 34285249, 2021).
lung squamous cell carcinoma (1 paper, 2025). "Next, we utilized spatial transcriptome data to further assess the spatial distribution of CTU2 and malignant cells in BRCA, lung squamous cell carcinoma (LUSC), and PAAD." (PMID 40375999, 2025).
mesothelioma (1 paper, 2025). A usually malignant and aggressive neoplasm of the mesothelium which is often associated with exposure to asbestos. "Univariate Cox regression analyses revealed that high CTU2 mRNA expression was significantly associated with OS and DSS across multiple cancers, particularly in ACC, KIRC, lower-grade glioma (LGG), mesothelioma (MESO), and sarcoma (SARC)." (PMID 40375999, 2025).
pancreatic adenocarcinoma (1 paper, 2025). "We randomly selected common tumor types for specific analysis, and the UMAP plots of BRCA, NSCLC, and pancreatic adenocarcinoma (PAAD) datasets intuitively showed that CTU2 is mainly expressed in malignant cells." (PMID 40375999, 2025).
paraganglioma (1 paper, 2025). A benign or malignant neoplasm arising from paraganglia located along the sympathetic or parasympathetic nerves. "Integrating TCGA and GTEx data further supported CTU2’s diagnostic potential in pheochromocytoma and paraganglioma (PCPG), PAAD, HNSC, and CHOL." (PMID 40375999, 2025).
skin cutaneous melanoma (1 paper, 2025). "In the spatial transcriptomics data of LIHC and skin cutaneous melanoma (SKCM), CTU2 is also primarily expressed in tumor tissue regions." (PMID 40375999, 2025).
stomach cancer (1 paper, 2025). "Further correlation analysis revealed a significant positive association between CTU2 expression and the expression of multiple isoforms of tRNA-Lys-TTT across various tumors, especially in BRCA, LIHC, stomach cancer (STAD), OV and TGCT." (PMID 40375999, 2025).
testicular germ cell tumor (1 paper, 2025). A germ cell tumor arising from the testis. "CTU2 mRNA levels increased with advancing clinical stage in cancers such as BRCA, HNSC, KIRC, KIRP, LIHC, LUSC, and testicular germ cell tumors (TGCT)." (PMID 40375999, 2025).
thyroid cancer (1 paper, 2025). "Kaplan-Meier curves indicated that elevated CTU2 mRNA expression correlated with poor prognosis in ACC, KIRC, LGG, LIHC, SARC, uveal melanoma (UVM), thyroid cancer (THCA) and LUSC." (PMID 40375999, 2025).
cancer (2 papers, 2021 to 2025). A tumor composed of atypical neoplastic, often pleomorphic cells that invade other tissues. "We also analyzed clinical phenotype data from TCGA to investigate CTU2 mRNA expression patterns across different clinical stages and their association with clinical features in various cancers." (PMID 40375999, 2025). "ROC curve analysis demonstrated that CTU2 has high diagnostic accuracy (AUC > 0.8) for eight cancer types, including READ, LUSC, LUAD, kidney renal papillary cell carcinoma (KIRP), KIRC, kidney chromophobe (KICH), COAD, and bladder urothelial carcinoma (BLCA)." (PMID 40375999, 2025). "Thus, not only does CTU2 contribute to cancer progression, but its modified tRNA is also linked to poor prognosis in various tumors." (PMID 40375999, 2025). "Experiments in vitro further confirmed that CTU2 promotes cancer behavior by enhancing cell proliferation and migration." (PMID 40375999, 2025). "We also utilized the TIMER 2.0 database to explore the correlation between CTU2 expression and the infiltration of specific immune cell types across various cancers." (PMID 40375999, 2025). "This signature was created by selecting the top 150 significantly upregulated and 150 significantly downregulated genes from comparisons between CTU2-high and CTU2-low expressing patients across various cancer types." (PMID 40375999, 2025). "We then investigated the differential promoter DNA methylation status of CTU2 between cancer and adjacent normal tissues by using UALCAN." (PMID 40375999, 2025). "With regards to copy number variation, a higher prevalence of copy number gains was observed in CTU2 genes across various cancers such as ACC, KIRC, KIRP, and others." (PMID 40375999, 2025). "Subsequently, Clinicopathological staging analysis, OS analysis, and DSS analysis also revealed a close correlation between CTU2 expression and the clinical prognosis of various cancers, particularly in KIRC and LIHC." (PMID 40375999, 2025). "Overall, this study provided a comprehensive overview of genetic landscape of CTU2 across cancer types, providing new insights and support for the role of tRNA modification enzymes in cancer therapy." (PMID 40375999, 2025). "Given the emerging novel role of tRNA in actively regulating gene expression and the crucial role of CTU2-mediated mcm5s2U tRNA modification, a comprehensive analysis of CTU2 in multiple cancers is extremely necessary." (PMID 40375999, 2025). "We further examined CTU2 expression across different molecular tumor subtypes and found distinct gene expression profiles for specific cancers." (PMID 40375999, 2025). "Firstly, we utilized the ESTIMATE database to investigate the impact of CTU2 expression on immune cell infiltration in human cancers." (PMID 40375999, 2025). "Given the prognostic significance of CTU2 in immune infiltration, we proceeded to investigate its predictive impact on cancer immunotherapy response." (PMID 40375999, 2025). "The drug sensitivity data from the GDSC database and DNA methylation data from cBioPortal and UALCAN further support the important role of CTU2 in various cancers." (PMID 40375999, 2025). "This analysis identified several drugs, such as Docetaxel_1007, Dactolisib_1057, Lapatinib_1558, and Tamoxifen_1199, with their sensitivity correlating with CTU2 expression levels, demonstrating a cancer-type-dependent response." (PMID 40375999, 2025). "Based on the mRNA expression levels of CTU2 in malignant tumor cells, we classified the tumor cells into two groups: those with high CTU2 expression and those with low CTU2 expression." (PMID 40375999, 2025). "Initially, the TCGA and GTEx databases were utilized for a comprehensive pan-cancer analysis of CTU2 mRNA expression profiles." (PMID 40375999, 2025). "Given the role of CTU2 across cancers, we next map the expression profile of its modified tRNAs in a pan-cancer context." (PMID 40375999, 2025).
cancer (continued). "Hence, the abnormal increase in CTU2 mRNA expression in certain cancers likely stems from both CNV alterations and reduced DNA methylation levels." (PMID 40375999, 2025). "Notably, MS-275, STOCK1N.35874, and NU.1025 consistently exhibited significantly lower scores across multiple cancer types, suggesting their potential to counteract the pro-oncogenic effects of CTU2." (PMID 40375999, 2025). "CTU2 may serve as a valuable prognostic and immunotherapeutic biomarker across multiple cancer types, providing new insights into tumor treatment strategies and immune evasion from the perspective of tRNA modifications." (PMID 40375999, 2025). "To further investigate the potential biological functions of CTU2 in pan-cancer, we examined whether cancer cell lines expressing high levels of CTU2 differ functionally from those with low levels." (PMID 40375999, 2025). "Therefore, this study systematically analyzes the expression, prognostic relevance, and functions of CTU2 across various cancer types, aiming to provide a potential intervention strategy for tumors through CTU2-mediated tRNA mcm5s2U modification." (PMID 40375999, 2025). "Additionally, the expression of CTU2 was found to be correlated with T stage, N stage, and M stage in various cancers." (PMID 40375999, 2025). "We believe that developing specific inhibitors or activators targeting CTU2 could significantly improve the disease progression and prognosis for cancer patients." (PMID 40375999, 2025). "In terms of function and mechanism, GSEA revealed that CTU2 may contribute to numerous critical cancer-related pathways and biological processes." (PMID 40375999, 2025). "Altogether, results from in vitro and in vivo were consistent with the findings from prognostic analyses and gene set enrichment analysis, indicating that CTU2 may serve as an oncogene in cancer." (PMID 40375999, 2025). "However, the relationship between CTU2 expression and various cancer types remains insufficiently explored." (PMID 40375999, 2025). "Notably, the transcription factor USF1 was identified as a regulator of CTU2 expression and has been confirmed to be an oncogene widely expressed in multiple cancer types." (PMID 40375999, 2025). "Our co-expression analysis has revealed a close association between CTU2 and the expression of these genes involved in chemokines, chemokine receptors, and MHC across different cancers, strongly suggesting that CTU2 could be indispensable for immunotherapy in diverse tumor types." (PMID 40375999, 2025). "CTU2 may contribute to several key cancer-related pathways and biological processes." (PMID 40375999, 2025). "Pan-cancer data from TCGA, GEO, and CPTAC were used to analyze CTU2 expression and its prognostic value." (PMID 40375999, 2025). "Knockdown or knockout of CTU2 impaired the proliferation of various cancer cell lines, with the gene effect scores being negative in nearly all of the cell lines, indicating a crucial gene dependency on CTU2 in the majority of cancer cells." (PMID 40375999, 2025). "Furthermore, in this study, we also revealed that two tRNA regulators, CTU2 and XPOT, may be functionally interconnected with METTL1 in cancer." (PMID 34285249, 2021). "Furthermore, functional annotation and pathway analysis of METTL1-associated proteins revealed that, in addition to METTL1 cofactor WDR4, two tRNA regulators, CTU2 and XPOT, may be functionally interconnected with METTL1 in human cancer." (PMID 34285249, 2021). "Interestingly, we also observed a negative correlation between CTU2 expression and the gene dependency of canonical tumor suppressor genes, such as PTEN and RUNX3, with these genes becoming less essential in CCLE-included cancer cell lines overexpressing CTU2." (PMID 40375999, 2025).